BMF (Bcl2 modifying factor)
Diseases named in the same sentence as BMF in open-access papers (continued):
Sharing a sentence is not in itself a finding about the gene and the disease.
cancer (28 papers, 2010 to 2026). A tumor composed of atypical neoplastic, often pleomorphic cells that invade other tissues. "This highlights the role of BIM and BMF in mediating the apoptotic response induced by MEKi+HDACi in TPM cancers." (PMID 40560846, 2025). "Conversely, a ligand for the cancer stem cell receptor CD44 led to reductions in BMF, BIM, and apoptosis." (PMID 37761989, 2023). "Transcription profiling identified the upregulation of proapoptotic BMF gene in cancer cells that are sensitive to TEAD inhibition." (PMID 36300789, 2022). "BMF expression was detected in various normal and cancer cells." (PMID 40849581, 2026). "Our observations suggested that the increased expression of BIM and BMF that results from SNAI2 knockdown may enhance apoptosis in TPM cancer cells treated with MEK1/2 and HDAC inhibitors." (PMID 40560846, 2025). "Moreover, we noted that increased expression of a proapoptotic BMF gene correlates with response to TEAD inhibition in some cancer cell lines." (PMID 36300789, 2022). "Though BMF has received relatively less attention than other pro-apoptotic proteins in the context of cancer, an increasing amount of literature links its regulation to mechanisms of anti-cancer agents." (PMID 34065488, 2021). "The EGFR-FOXO6-SOX2 signaling pathway regulating expression ofthe BIM and BMF apoptotic factors thus identifies a feedback loop that may attenuatethe effectiveness of anti-EGFR therapy in cancer and contribute toward the ultimatedevelopment of drug resistance." (PMID 25686219, 2015). "Thus, anEGFR-SOX2-BCL2L1 pathway may be implicated in cancer cells with wild-type EGFR,whereas the EGFR-FOXO6-SOX2-BIM/BMF pathway we describe is specific for cells thatare dependent on mutant EGFR signals for their survival." (PMID 25686219, 2015). "In conclusion, our study unravels a novel role of MEK1/2, HDACs, and SNAI2 in orchestrating survival of a specific class of cancers, driving the expression of two well-known mediators of apoptosis in aggressive cancers, BIM and BMF." (PMID 40560846, 2025). "Taken together, our data suggest that inhibition of YAP/TAZ synergizes with KRAS G12C inhibitors to induce robust apoptosis in cancer cells via upregulating the expression of proapoptotic genes such as BCL2L11, BMF, and PUMA." (PMID 39704172, 2024). "Peptides and small molecules that inhibit BCL-2 proteins have been developed and are able to rescue the ability of cancer cells to undergo apoptosis by releasing BH3-only proteins such as BIM and BMF." (PMID 37761989, 2023). "Genes such as PYGM, BMF, MBNL3, DENND6A, REEP5, KLF6 and ITM2C are potentially regulated by circYPEL2 and involved in cancer-specific pathways, which are needed to be validated in further studies." (PMID 35052380, 2021). "Contrary to our expectations, we found that hESCs express the pro-apoptotic BH3-only BCL-2 family members NOXA, BIK, BIM, BMF, and PUMA at levels far greater than that seen in the seven human primary cells, hESC-derived neural stem cells, or cancer lines." (PMID 22174832, 2011). "Our findings indicate that hESCs express elevated levels of the pro-apoptotic BH3-only BCL-2 family members NOXA, BIK, BIM, BMF and PUMA when compared with differentiated cells and cancer cells." (PMID 22174832, 2011). "We also provide compelling evidence that the transcription factor SNAI2, in conjunction with MEK1/2 signaling, drives the hybrid EMT phenotype in TPM cancers, facilitating survival and apoptosis resistance through epigenetic suppression of apoptotic markers like BIM and BMF." (PMID 40560846, 2025).
cancer (continued). "We found that pro-apoptotic BIM and BMF levels are suppressed by constitutive MEK1/2 signaling in these cancers and disrupting this pathway triggers BIM and/or BMF-dependent apoptosis across various TPM cancer types." (PMID 40560846, 2025). "In cancer cells, both BIM and BMF are frequently bound by BCL-2 anti-apoptotic proteins." (PMID 37761989, 2023). "BBC3/PUMA, BMF, BIM, and PMAIP1/NOXA are all more upregulated in cancer cells." (PMID 36195608, 2022). "Interestingly, several genes were known to be regulated by the TGFβ pathway (e.g., BMF, COL4A4) and/or expressed in several cancers (e.g., HOTAIR, MRC2, POSTN, SPARC)." (PMID 34830779, 2021). "Differential upregulation of BBC3/PUMA, BMF, BIM, and PMAIP1/NOXA between non-transformed and cancer cells was confirmed by RT-PCR." (PMID 36195608, 2022).
tumor (21 papers, 2014 to 2025). "The peptide increases levels of the pro-apoptotic protein BMF and substantially reduces levels of the pro-survival protein survivin in all tumor cells tested thus far." (PMID 40358191, 2025). "Simultaneously, we performed a parallel analysis of the levels of p-AMPK, p-mTOR, p-ULK1, and BMF in tumor tissues via Western blotting." (PMID 39598428, 2024). "Both these pan-HDIs selectively killed transformed cells and induced tumor cell-selective up regulation of the pro-apoptotic BMF gene." (PMID 25605023, 2015). "SAHA, a pan-HDAC inhibitor, was previously shown to induce tumor cell selective expression of the BMF gene." (PMID 25605023, 2015). "In addition to observing that the peptides significantly elevate BMF in multiple tumor lines, we found that BMF knockdown was sufficient to suppress their apoptotic activities." (PMID 34065488, 2021). "Consequently, combined inhibition of ERK1/2 signalling and MCL1 is synthetic lethal, inducing profound, synergistic BAK/BAX-, BIM- and BMF-dependent apoptosis and tumour regression." (PMID 31727888, 2019). "Consequently, BRAF or MEK1/2 inhibitors are synthetic lethal with the MCL1 inhibitor AZD5991, driving profound tumour cell death that requires BAK/BAX, BIM and BMF, and inhibiting tumour growth in vivo." (PMID 31727888, 2019). "miR-221 can promote tumor growth in HCC cells by targeting the expression of p57 (CDKN1C), p27 (CDKN1B), and BCL-2-modifying factor (BMF)." (PMID 40260417, 2025). "To extend our findings into antimitotic chemotherapy response, we investigated the FOXM1-dependent co-regulation of BMF and BUB1B expression in the context of tumor cell treatment." (PMID 34035233, 2021). "As a result, inhibition of ERK1/2 signalling in tumour cells invariably promotes the expression of pro-apoptotic BIM, BMF and/or PUMA11." (PMID 31727888, 2019). "Of note, BIM, BMF and NOXA levels were higher in Mcl-1tg/MLL-AF9 and BCL-2tg/MLL-AF9 than WT/MLL-AF9 tumours." (PMID 30470795, 2019). "We further investigated its effects on the apoptosis and autophagy of tumor cells and whether these processes were related to the AMPK–mTOR–ULK1/BMF pathway." (PMID 39598428, 2024). "However, when extrapolating our findings into a wide tumor context, we found that FOXM1-dependent BMF repression appears disrupted in anoikis-resistant cells." (PMID 34035233, 2021). "This is also true in other tumour lineages, such as CRC; however, whereas increased BIM and BMF primed CRC cells to undergo substantial apoptosis following treatment with the BCL2/BCL-w/BCL-XL inhibitor navitoclax/ABT-26311,25,26, this combination was notably less effective in melanoma." (PMID 31727888, 2019).
infection (2 papers, 2015 to 2022). The state of being infected such as from the introduction of a foreign agent such as serum, vaccine, antigenic substance or organism. "In the spleen, the level of BMF mRNA was downregulated 60 and 90 days after infection (p < 0.05)." (PMID 26690468, 2015). "In the liver, the level of BMF mRNA was downregulated 10 and 70 days after infection." (PMID 26690468, 2015). "Finally, in the blood the level of BMF mRNA expression was downregulated 30, 40, and 90 days after infection (p < 0.05)." (PMID 26690468, 2015).
BMF also shares sentences with these, for which no sentence is quoted: colorectal cancer (3 papers); 22q11.2 deletion syndrome (1); autoinflammatory syndrome (1); B cell lymphoma (1); brain ischemia (1); cerebral infarction (1); complement deficiencies (1); endometrial cancer (1); papillary thyroid carcinoma (1); status epilepticus (1); Thrombocytopenia (1); tongue cancer (1); uterine cancer (1); viral myocarditis (1).